LRP6 (LDL receptor related protein 6)
Diseases named in the same sentence as LRP6 in open-access papers (continued):
Sharing a sentence is not in itself a finding about the gene and the disease.
cancer (continued). "Nonetheless, it will be important in future studies to confirm this function of LRP6 in a more relevant model of human cancer such as patient-derived CRC organoids (e.g., with or without BRAF mutation)." (PMID 34359960, 2021). "LRP6 is highly expressed in several cancer cell lines and overexpression of LRP6 promotes cancer cell proliferation." (PMID 34589484, 2021). "miR-202 also restrains cell proliferation in humanhepatocellular cancer via suppressing LRP6 expressionpost-transcriptionally." (PMID 31863664, 2020). "The expression of LRP6 was found to be upregulated in these cancers and altered LRP6 leads to abnormal Wnt protein activation." (PMID 31031810, 2019). "Niclosamide, another inhibitor targeting LRP6 on the cell surface, also induces cancer cell apoptosis." (PMID 31382613, 2019). "In HCC cell lines, we also proved enhanced stem-like characteristics of cancer cells were related to high expression of LRP6." (PMID 28870205, 2017). "LRP6 promotes cancer metastasis by participating in the canonical Wnt pathway in a variety of cancers such as triple negative breast cancer." (PMID 29383201, 2017). "Considering that the unlimited cell proliferation is an important feature of cancer cells, thus LRP6 was chosen for further studies." (PMID 28880263, 2017). "Positive p-LRP6 was found in 92 of 115 cases (80.0%) of advanced carcinoma (T3 and T4), while early carcinomas (T1 and T2) showed positive staining in just 35.3% (24/68) (p<0.001, χ2=36.801)." (PMID 29312635, 2017). "LRP6 is a well-known activator of beta-catenin, leading to pro-proliferation, pro-metastasis and anti-apoptosis in several cancer types including HCC." (PMID 25240815, 2014). "Meanwhile, LRP6 is also found to be correlated with cancer initiation and progression and significantly overexpressed in various types of human cancers, such as liver cancer, colon cancer, and kidney tumor." (PMID 25491321, 2014). "Mechanistically, NDRG1 can interact with Wnt receptor LRP6 and block Wnt/β-catenin signaling in cancer cell lines." (PMID 23741453, 2013). "Together, these results suggest that Wnt co-receptor LRP6 is a potential therapeutic target for cancer, and that Mesd protein and its peptide have therapeutic value in Wnt-dependent cancers." (PMID 23469146, 2013). "We demonstrate herein that niclosamide is a potent Wnt/β-catenin signaling inhibitor by inducing LRP6 degradation in cancer cells, and displays an excellent anticancer activity in vitro." (PMID 22195040, 2011). "By comparing the expression of LRP6 in 33 cancer types and their corresponding normal tissues." (PMID 38226972, 2024). "LRP6 serves as a member of the Wnt/β-catenin signalling pathway, driving cancer progression (1." (PMID 38250152, 2024). "Various genetic risk factors for cancer and CVD have been identified, and reports suggest that mutations in LRP6, a Wnt binding protein, may cause CVD and other cancers." (PMID 38404658, 2024). "LRP6 acted as a regulator involved in maintaining lipid homeostasis via nutrient-sensing mTOR pathways while promoting aberrant lipid lipogenesis and regulating fatty acid synthesis in cancer cells." (PMID 38250152, 2024). "Our findings indicate that LRP6 could behave differently in different cancers based on genetic abnormalities related to the Wnt/β-catenin pathway." (PMID 36983771, 2023). "Moreover, since LRP6 is upregulated in many cancer types in vivo, this offers solid bases upon which to further investigate the promising oncolytic properties of CDV-OP." (PMID 36645301, 2023). "In their study, this circRNA was validated to deactivate miR-338-3p, thus triggering cancer progression and glycolysis by increasing the level of low-density lipoprotein receptor-related protein 6 (LRP6), which acts as a coreceptor of WNT ligands and activates WNT/β-catenin signaling." (PMID 35055115, 2022). "LRP5 and LRP6 have been shown to play important roles in a broad panel of cancers." (PMID 36012187, 2022).
cancer (continued). "Interestingly, LRP6 alterations belong to inclusion criteria in clinical trials using inhibitors of porcupine in various cancers, highlighting the presumed critical role of LRP6 in cancer development." (PMID 31412666, 2019). "The elucidation of the LRP6 interactome may be one additional step to further understand LRP6 functions in cancer development." (PMID 31412666, 2019). "Thus additional blockade of LRP6-independent Wnt signaling should be applied for maximal Wnt signaling inhibition in cancer cells." (PMID 29335534, 2018). "LRP6 is a well-recognized coreceptor for Wnt signaling in cancer." (PMID 28418856, 2017). "LRP6 was previously involved in the regulation of cancer cells." (PMID 28880263, 2017). "In silico analysis showed that the designed peptides are readily bound to the Wnt- and DKK-binding interfaces of LRP6, and may be considered as possible therapeutic modalities for inhibiting Wnt-mediated cancer progression and invasion." (PMID 28234935, 2017). "Unlike β-catenin and adenomatous polyposis coli (APC), both of which are frequently mutated in cancer, oncogenic mutations have not been observed in LRP6." (PMID 28966723, 2017). "Therefore, miRNA-126-3p and miRNA-454 as well as LRP6 are potential targets for the treatment of cancer angiogenesis and metastasis." (PMID 29383201, 2017). "Reports on the expression pattern and functional roles of LRP6 in cancers are scanty." (PMID 22570728, 2012). "In addition to LRP6, co-receptor LRP5 was also found to be implicated in Wnt/β-catenin pathway in cancers." (PMID 22570728, 2012). "However, evidence about the role of LRP6 in tumorigenesis is scanty, with only few reports showing the potential oncogenic role of LRP6 in cancers." (PMID 22570728, 2012). "LRP6 is expressed in human cancer cell lines and up-regulated in human malignant tissues." (PMID 22195040, 2011). "In addition, shared molecular and genetic pathways (such as adenosine 5’ monophosphate-activated protein kinase, LRP6 mutation, and Wnt signaling pathway) may also explain the similarities between CHD and cancer." (PMID 38124895, 2023). "Hence, circ_FBLIM1 may be transported between cancer cells to regulate the miR-338-3p/LRP6/WNT/β-catenin axis." (PMID 35055115, 2022). "Similarly, dysregulation of LRP6 is also involved in cancer." (PMID 34589484, 2021). "In addition, it is reported that four downregulated genes of AKT1, CLECSF7, FGFR3, and LRP6 served as candidate genes and correlated with suppressing the biological processes in the cell cycle of cancer progression and the downstream signaling pathways of malignancy of melanocytic tumorigenesis." (PMID 33250779, 2020). "Similarly, LRP6′s role in cancer progression has been controversial." (PMID 31382613, 2019). "Therefore, LRP6 protein clearly represents a pertinent actionable target for cancer therapy." (PMID 31412666, 2019). "Also, it was found that LRP6 would lead to the cancer disease." (PMID 31239472, 2019). "The peptide-LRP6 complexes were highly stable and compact, and therefore, could be considered as possible therapeutic agents for hindering Wnt signaling pathway in the cancers which are dependent on function of this signaling pathway." (PMID 28234935, 2017). "A recent study using cancer cell lines reveals that the tumor metastasis suppressor gene, NDRG1, represses Wnt/β-catenin signaling by directly interacting with the Wnt receptor, LRP6, consequently causing the suppression of Wnt/β-catenin target gene, ATF3 expression." (PMID 23741453, 2013).
cancer (continued). "By using different experimental approach, data from our present study and Bu's group have concordantly provided evidence that overexpression of cell-surface Wnt co-receptor LRP6 may play an important role in cancer progression through activation of the Wnt/β-catenin signaling pathway." (PMID 22570728, 2012). "The results showed that the expression level of LRP6 correlated with the infiltration level of immune cells such as T cells CD8+, T cells CD4+, neutrophils, macrophages, dendritic cells, etc., in 33 cancer types." (PMID 38226972, 2024). "In particular, low-density lipoprotein receptor-related protein 6 (LRP6), an essential receptor for Wnt signaling, directly interacting with Wnt ligands, has been shown to be involved in multiple cancers." (PMID 37873862, 2023). "The WNT signaling in our study is altered by the deregulation of APC, FZD1, FZD6, LRP6, and WNT10B, which are included by KEGG in the process of cancer proliferation." (PMID 34715892, 2021). "Overall, in cancer cells, Wnt ligands bind with members of the Frizzled (Fz) family of serpentine receptors, as well as the LRP5 or LRP6 coreceptors to activate and recruit the phosphoprotein Dishevelled (DSH)." (PMID 34344421, 2021). "In this cluster, Rac Family Small GTPase 1 (RAC1), Caveolin 1 (CAV1), Low-density lipoprotein receptor-related protein 6 (LRP6) and collagen type I alpha 1 chain (COL1A1) were identified as proteins shown to promote EMT in various cancer." (PMID 33050615, 2020). "Little is known about the cancer tissue expression of FZD4, LRP5, LRP6 proteins, and we assessed their behavior for the first time in a clinical BC cohort." (PMID 31336689, 2019). "Herein, we focus on the specific roles of LRP6 in the control of the WNT/β-catenin pathway and in the regulation of tissue homeostasis and carcinoma development." (PMID 31412666, 2019). "LRP6 acetylation triggers LRP6 phosphorylation at the level of tyrosine residues, activating the WNT signaling and self-renewal of CD110+ cancer stem cells." (PMID 29652830, 2018). "For example, genes with Motif 1 in Molecular Mechanisms of Cancer pathway include MAPK1, BRAF, SMAD2, FZD5, FZD8, NOTCH1 and LRP1, whereas genes with Motif 2 and/or Motif3 in the same pathway include LRP5, LRP6, MDM2, CTNND1, SMAD3, SMAD4 and SMAD7." (PMID 26040697, 2015). "As an activator of the WNT pathway through mediating the phosphorylation of LRP6 in the G2/M phase, CDK14 was found that it could promote the progression of several cancers." (PMID 35479936, 2022). "As ECM-CAFs originate from resident liver fibroblasts, it is interesting to note that in hepatocytes, Wnt/β-catenin signaling can synergize with insulin signaling through IGF1R, LRP5, and LRP6 34, which were concomitantly enriched in ECM-CAF-cancer cell LR interactions." (PMID 36438498, 2022). "Nicola confirmed that Kremen-1, but not lipoprotein receptor-related protein 6 (LRP6), immunoprecipitated with DKK3 in cancer-associated fibroblasts, and the mRNA levels of Kremen-1 were not altered after DKK3 silencing." (PMID 32331523, 2020). "Therefore, our data suggest that circ-LRP6 is a critical regulator in ESCC carcinogenesis, it will be of great interest to explore its role in other malignant tumors." (PMID 32867570, 2020). "LRP5, LRP6, and LRP8 have been shown to play important roles in a broad panel of cancers." (PMID 31031810, 2019). "Furthermore, the inhibitory effects of niclosamide on LRP6 expression/phosphorylation and Wnt/β-catenin signaling were conformed in human prostate PC-3 and DU145 and breast MDA-MB-231 and T-47D cancer cells." (PMID 22195040, 2011). "The modular nature of Wnt discrimination of LRP6 from the “non-canonical” coreceptors opens the possibility of swapping the linker domain to create “designer Wnts” with altered functions in regenerative medicine and cancer biology." (PMID 36893265, 2023).
cancer (continued). "Although overexpression of LRP6 is observed in these types of cancer, it is not known whether the function of LRP6 differs depending on genetic abnormalities in the Wnt/β-catenin pathway." (PMID 36983771, 2023). "Although LRP6 is expressed in normal tissue, attenuated CDV-OP could act as an attractive choice for oncolytic virotherapy, as cancer cell-specificity may also be controlled by defective interferon signaling, which is often found to be the case in cancer cells." (PMID 36645301, 2023). "Although the aberration of LRP6 is observed in many types of cancers with various gene mutation frequencies in the Wnt/β-catenin pathway, there are no reports showing whether LRP6 could behave differently in cancers based on Wnt/β-catenin pathway genetic abnormalities." (PMID 36983771, 2023). "Interestingly, unlike HEK293 cells where the STF reporter activity can be inhibited fully by anti-LRP6 antibodies (mono or bispecific, with the difference in IC50 but not maximum level of inhibition), we observed about 50% suppression of Wnt/β-catenin reporter activity in cancer cells." (PMID 29335534, 2018). "LRP6 knockdown was not sufficient to alter clonogenic potential nor anchorage-independent growth of HCT116 and SW48 cancer cells." (PMID 34359960, 2021). "In the field of cancer research, especially for HCC, the negative role of CCN2 and the interaction regulation mechanism between CCN2 and LRP6 are still unclear." (PMID 28870205, 2017). "Furthermore, MTT assay and CCK8 assay were performed to determine the effects of LRP5/6 knockdown on cancer cell viability and proliferation, which showed that knockdown with LRP5, but not LRP6 or β-catenin, significantly inhibited the cell viability and proliferation of HepG2 cells." (PMID 31881970, 2019).
infection (10 papers, 2010 to 2025). The state of being infected such as from the introduction of a foreign agent such as serum, vaccine, antigenic substance or organism. "In this study, we further explored the potential role of DKK1-LRP6 signalling in the migration and longevity of activated neutrophils in the infection site using BALB/c mice with PMNs deficient in LRP6 (LRP6NKO) or BALB/c mice deficient in both PMN LRP6 and platelet DKK1 (LRP6NKO DKK1PKO)." (PMID 39502693, 2024). "To study whether nuclear translocation of β-catenin in H. pylori-infected epithelial NCI-N87 cells depends on LRP6, Dvl2 or Dvl3, we performed an infection of stable knockdown cell lines deficient for LRP6, Dvl2 or Dvl3." (PMID 20137080, 2010). "In this study, we also demonstrated that neutrophils expressed LRP6, and the DKK1-LRP6 interaction promotes the infiltration of activated neutrophils in the infection site of BALB/c mice." (PMID 39502693, 2024). "Although receptor recycling can lead to lowered levels of surface receptor expression as a result of ligand activation, we examined the level of LRP6 expression on PMNs during infection." (PMID 39502693, 2024). "Whereas the genetic ablation of LRP6 rendered cells resistant to infection, ectopic expression in resistant LRP6KO cells restored susceptibility." (PMID 36645301, 2023). "On the other hand, the de-regulators of the Wnt pathway, namely, Naked-1 (Nkd-1) and phosphorylated Axin (pAxin) were reciprocally expressed to Wnt and LRP6 phosphorylation after 12 h of infection." (PMID 35336965, 2022). "miR-34a KO and miR-34a/b/c KO organoids also showed increased expression of Lrp6 and Fzd7, similar to the Wnt-independent organoids generated upon infection." (PMID 33579932, 2021). "In the presented work we used human gastric epithelial cells NCI-N87 to study LRP6- and Dvl-dependent regulation of β-catenin after infection with H. pylori." (PMID 20137080, 2010). "Our study aimed to elucidate the role of proximal Wnt signaling components low density lipoprotein receptor-related protein 6 (LRP6) and Dishevelled (Dvl) in the activation of β-catenin early after infection of gastric epithelial cells with H. pylori." (PMID 20137080, 2010). "Infection of AGS cells confirmed these data as H. pylori induced a similar phosphorylation of LRP6 compared to NCI-N87 cells." (PMID 20137080, 2010). "Phosphorylation of LRP6 was induced within 30 minutes after infection in a CagA- and VacA-independent manner." (PMID 20137080, 2010). "Given the percentage of MPO-positive neutrophils in LRP6NKO and LRP6NKO DKK1PKO infected mice is decreased in comparison to BALB/c infected mice, these data further confirm that the interaction of DKK1 and LRP6 is essential for the migration of activated neutrophils to the infection site." (PMID 39502693, 2024). "This suggests that DKK1 signalling via its receptor (LRP6) might also regulate the migration of activated neutrophils to the infection site." (PMID 39502693, 2024). "The mechanism involved in the upregulation of LRP6 expression is unclear but may be the result of cytokines or other mediators produced in response to infection as well as DKK1 itself." (PMID 39502693, 2024). "Interestingly, the data demonstrated that in our experimental conditions, only megalin and Lrp6 showed a significant decrease upon IV infection." (PMID 37727782, 2023). "Infection of gastric epithelial NCI-N87 cells with H. pylori induces rapid phosphorylation of the Wnt/β-catenin pathway co-receptor LRP6 independent of the cytotoxin-associated gene A (CagA) or vacuolating cytotoxin A (VacA)." (PMID 20137080, 2010). "Interestingly, the levels of MPO, CD11b and MHC class II positive PMNs of LRP6NKO and LRP6NKO DKK1PKO mice were comparable and were not significantly different from naïve mice, suggesting that the activation of PMNs upon infection is primarily through the LRP6 pathway." (PMID 39502693, 2024).
infection (continued). "However, the underlying process involved in LRP6 upregulation in infected BALB/c mice is unknown, and it may involve other host factors released during infection." (PMID 39502693, 2024). "E. chaffeensis was found to very strongly colocalize with the Wnt pathway coreceptor LRP5, and infection was significantly reduced in LRP5 and LRP6 RNA-silenced cells." (PMID 33883266, 2021). "Also, our recent work has established that DKK1 signaling via its receptor (LRP6) elevates NPA formation and the migration of activated neutrophils to the infection site." (PMID 40502169, 2025). "E. chaffeensis did not colocalize with LRP6 at early stages of infection, but silencing of LRP6 strongly reduced infection level in monocytes." (PMID 33883266, 2021). "We observed increased levels of phosphorylated LRP6 within 30 minutes post infection, which requires a functional T4SS, but not CagA or VacA." (PMID 20137080, 2010). "As in NCI-N87 cells, infection with H. pylori induced LRP6 phosphorylation independent of CagA or VacA, but required a functional T4SS." (PMID 20137080, 2010). "While these data suggest LRP6 may not be involved as a receptor for E. chaffeensis, silencing of LRP6 may still significantly inhibit infection through sufficiently blocking canonical signaling in THP-1 cells, which could result in low infection levels in these cells." (PMID 33883266, 2021).
cardiovascular diseases (8 papers, 2012 to 2024). "A previous study has shown similar findings that carriers of LRP6 mutations was associated with cardiovascular disease." (PMID 39512695, 2024). "Discovery of this disease-related LRP6 allele and its link to altered canonical Wnt signaling has provided novel risk factors and the development of advanced therapeutics for cardiovascular disease." (PMID 26046396, 2015). "As a co-receptor of the Wnt/β-catenin signaling pathway, LRP6 is a novel therapeutic target that plays an important role in the regulation of cardiovascular disease, lipid metabolism, tumorigenesis, and some classical signals." (PMID 37175248, 2023).
bone disorder (4 papers, 2012 to 2024). "LRP5 and LRP6 are coreceptors for the Wnt/β-catenin pathway, and mutations in these genes can lead to altered bone mass and increased susceptibility to bone disorders." (PMID 39371752, 2024). "Nevertheless, whether YAP activation/inhibition is a potent approach to treat skeletal diseases by dysregulated LRP6 needs further investigation." (PMID 36694134, 2023).